LINC00524 (long independently transcribed non-coding RNA 524)
Synonyms: formerly C14orf71
Gene: Long non-coding RNA gene on chromosome 14 (101,354,270 to 101,459,331, reverse strand). Ensembl gene ENSG00000259023.
Diseases named in the same sentence as LINC00524 in open-access papers:
LINC00524 is named in the same sentence as 4 diseases in open-access papers, as found by Europe PMC text mining. Sharing a sentence is not in itself a finding about the gene and the disease. The quoted sentences say what the papers report.
clear cell renal cell carcinoma (2 papers, 2022 to 2024). "Current biochemical analyses have demonstrated that LINC00524 is overexpressed in oral squamous and renal clear cell carcinoma relative to adjacent normal tissues and links with a poor prognosis for the patient." (PMID 38568058, 2024).
tumour (2 papers, 2022 to 2024). "The tumour growth rate and tumour weight of the LINC00524 overexpression group were significantly higher than the empty vector groups." (PMID 38568058, 2024). "We monitored the mice's body weight and tumour size, and the results showed that mice overexpressing LINC00524 had significantly reduced body weight relative to the control group." (PMID 38568058, 2024). "FIRRE, LINC01305, AC099850.3, AL512274.1, AC090246.1, MIAT, AC079921.2 and LINC00524 were differentially expressed in tumour and normal tissues." (PMID 36384476, 2022). "Similarly, in vivo experiments revealed that LINC00524 significantly enhances BC tumour proliferation and lung metastasis and is stably expressed in mice, exhibiting species conservation." (PMID 38568058, 2024). "The RNA pull‐down assay demonstrated an interaction between LINC00524 and TDP43 protein, and in vivo immunohistochemical staining revealed increased TDP43 expression in tumour tissues overexpressing LINC00524, which promoted BC lung metastasis." (PMID 38568058, 2024).
LINC00524 also shares sentences with these, for which no sentence is quoted: cancer (1 paper); non-small cell lung carcinoma (1).